ATF6 (activating transcription factor 6)
Diseases named in the same sentence as ATF6 in open-access papers (continued):
Sharing a sentence is not in itself a finding about the gene and the disease.
chordoma (1 paper, 2019). Chordomas are rare malignant tumors arising from embryonic remnants of the notochord in axial skeleton. "In this study, we find that Doxo or Irino induce a moderate UPR in chordoma cells as shown by an increased expression of CHOP, BiP, ATF4, ATF6, and XBP1-s." (PMID 31767864, 2019).
chronic hepatitis (1 paper, 2020). An active inflammatory process affecting the liver for more than six months. "A study of liver samples from untreated patients with chronic hepatitis identified ‘ER-stressed hepatocytes’ in clusters scattered in the liver parenchyma presented with protein expression of ATF-6, IRE1α and PERK." (PMID 32005714, 2020).
chronic hepatitis B (1 paper, 2017). "We then examined the mRNA levels of ASNS and ATF6 in 90 HCC patients, 77 chronic hepatitis B patients and 70 controls." (PMID 28629319, 2017).
citrullinemia (1 paper, 2022). Citrullinemia is an autosomal recessively inherited disorder of urea cycle metabolism and ammonia detoxification characterized by elevated concentrations of serum citrulline and ammonia. "Moreover, the ATF6 c.82+5G > T mutation led to intron retention, while ASS1 mutations c.773+4A > C and c.970+5G > A were identified in patients with citrullinemia." (PMID 35309121, 2022).
complication (1 paper, 2018). Any disease or disorder that occurs during the course of, or because of, another disease, treatment, or procedure. "TRIB3 rs2295490, ATF6 rs12086247, and SMARCD3 rs58125572 genetic variants are associated with specific treatment protocols and with the incidence of diabetic vascular complications." (PMID 30618737, 2018).
cone dystrophy (1 paper, 2020). An inherited ocular disorder characterized by the loss of cone cells, the photoreceptors responsible for both central and color vision. "ATF6 was activated in multiple tissues throughout development, can be induced by ER stress, and is upregulated in zebrafish disease models of cone dystrophy and ALS." (PMID 31852729, 2020).
congenital nephrotic syndrome (1 paper, 2022). "Nevertheless, activation of ATF6 only is not unprecedented, as it was described for instance for ER-retained nephrin mutants associated with congenital nephrotic syndrome of the Finnish type." (PMID 36345359, 2022).
Dengue virus infection (1 paper, 2007). "The IRE1-XBP1 axis has been recently shown to be activated in cells infected with JEV and Dengue whereas the ATF-6 pathway has been reported to be activated upon HCV infection." (PMID 17888185, 2007). "Our data show that the ATF6 pathway is also activated by Dengue virus infection." (PMID 17888185, 2007). "We find that upon Dengue virus infection, A549 cells elicit an UPR which is observed at the level of translation attenuation (as visualized by the phosphorylation of eIF2alpha) and activation of specific pathways such as nuclear translocation of ATF-6 and splicing of XBP-1." (PMID 17888185, 2007).
diabetic cardiomyopathy (1 paper, 2022). Diabetic cardiomyopathy is a disorder of the heart muscle in people with diabetes. "At the same time, Astragalus polysaccharides can reduce the apoptosis rate of cardiomyocytes by inhibiting the expression of ATF6 and PERK, which are related to the ER stress pathway in diabetic cardiomyopathy rats and high glucose-treated H9C2 cells." (PMID 36091599, 2022).
diffuse large B-cell lymphoma (1 paper, 2025). "This study analyzes the expression and functional role of activating transcription factor 6 (ATF6) in diffuse large B-cell lymphoma (DLBCL) and its effects on disease progression." (PMID 40205285, 2025).
Down syndrome (1 paper, 2020). "Next, since oxidative damage leads to GRP78 dysfunction and consequent aberrant activation of UPR, as previously observed in down syndrome (DS), we investigated the activation of the three major arms of UPR pathways mediated by PERK, IRE, and ATF6." (PMID 32610629, 2020).
E. coli infection (1 paper, 2022). "Our results showed that 2-APB and BATPA-AM reduced the expression of GRP78 and UPR-related proteins (p-IRE1, p-eif2α and ATF6) during E. coli infection, which implies that cytosolic Ca2+ may regulate the degree of inflammation by regulating ERS." (PMID 36430657, 2022).
embryonic carcinoma (1 paper, 2024). "➢ATRA (10–20 μM) induced splicing of XBP1 mRNA in 1 h in HuH-7 cells.➢ATRA (10–20 μM) induced accumulation of XBP1 protein in the nucleus of HuH-7 cells in 8 h.✧In P19 embryonic carcinoma cells, ATRA induced the upregulation of several UPR-related genes (Atf6, Xbp1, Chop)." (PMID 38786033, 2024).
emphysema (1 paper, 2019). "We used Western blot method to assess the activation of IRE1 and ATF6 pathways in CS induced emphysema rat lung." (PMID 31281258, 2019). "ATF6 was activated in the CSE2W group, which may indicate that ATF6 pathway exerts its effect in pre-emphysema group." (PMID 31281258, 2019). "Our work showed that in rats the IRE1 pathway of UPR is up-regulated in CS induced-emphysema, however, ATF6 expression is not." (PMID 31281258, 2019). "However, the expression and activation of IRE1 and ATF6 pathways in CS-induced emphysema has not been reported previously." (PMID 31281258, 2019).
endometriosis (1 paper, 2024). The growth of functional endometrial tissue in anatomic sites outside the uterine body. "Using clinical samples, we demonstrated that the protein levels of PERK, p-PERK, ATF6, GRP78, and BOK were decreased in endometriosis using clinical samples." (PMID 38549776, 2024).
endotoxemia (1 paper, 2025). "The increased GRP78, phospho-IRE1α, phospho-PERK, and cleaved ATF-6 expression induced by endotoxemia and MV at VT = 30 mL/kg were substantially reduced after administration of ER stress inhibitor 4-PBA." (PMID 40565223, 2025). "In mice with endotoxemia subjected to VT = 30 mL/kg, 4-PBA prevented the activation of GRP78, phospho-IRE1α, phospho-PERK, and ATF-6 induced by MV with VT = 30 mL/kg." (PMID 40565223, 2025). "Western blot analyses revealed greater GRP78, phopho-IRE1α, phosphor-PERK, and cleaved ATF-6 expression in mice with endotoxemia subjected to VT = 30 mL/kg than in those without endotoxemia subjected to VT = 30 mL/kg and the nonventilated control mice." (PMID 40565223, 2025).
epilepsy (1 paper, 2022). A brain disorder characterized by episodes of abnormally increased neuronal discharge resulting in transient episodes of sensory or motor neurological dysfunction, or psychic dysfunction. "Our data unambiguously corroborates that the ATF6 activators AA147 and AA263 enhanced the folding and reduced the degradation of the epilepsy-causing variant subunits, leading to their productive trafficking to the Golgi and onward to the plasma membrane." (PMID 35477478, 2022).
esophagitis (1 paper, 2023). An acute or chronic inflammatory disease affecting the esophageal wall. "ATF-6, XBP-1, DNAJC-9, and NF-2-L-2 levels were significantly decreased after treatment in patients without esophagitis in the endoscopic examination." (PMID 37158535, 2023).
Flavivirus Infections (1 paper, 2014). Infections with viruses of the genus FLAVIVIRUS, family FLAVIVIRIDAE. "Other Flavivirus infections, including HCV, JEV, and DENV2, also induce cleavage of ATF6, nuclear translocalization of ATF6 and increases in chaperone proteins expression." (PMID 25140166, 2014).
glaucoma (1 paper, 2025). Increased pressure in the eyeball due to obstruction of the outflow of aqueous humor. "Overall, our findings demonstrated that the optoenergetic activation of mt-EcGAPR rescued mitochondrial hypometabolism, alleviated the ER stress–ATF6 axis, and inhibited pyroptosis, leading to enhanced neuroprotective effects against glaucoma." (PMID 41162360, 2025). "Our findings demonstrate that in low-MMP conditions, such as glaucoma, the optoenergetic activation of mt-EcGAPR effectively rescues mitochondrial dysfunction by increasing ATP production, inhibiting ROS accumulation, and suppressing ER stress-ATF6-GSDMD axis-mediated pyroptosis." (PMID 41162360, 2025).
Hepatitis (1 paper, 2026). Inflammation of the liver. "Hepatocyte-specific ATF6α activation in mice induced progressive hepatitis with ER stress, immunosuppression and hepatocyte proliferation." (PMID 41639449, 2026).
HIV-1 infection (1 paper, 2022). The type species of lentivirus and the etiologic agent of acquired immunodeficiency syndrome (AIDS). "Notably, chronic METH (50 nM; blue bars) exposure significantly increased expression of UPR arm IRE1α by 50% (p < 0.05) without increasing BiP, ATF6, or PERK, and HIV-1 infection (500 RT; red bars) induced significant increases in all arms and their binding partner (p < 0.05)." (PMID 35784841, 2022).
hypertriglyceridemia (1 paper, 2021). A laboratory test result indicating elevated triglyceride concentration in the blood. "The improved insulin sensitivity in ATF6α-deficient DO mice can be due to partial suppression in the development of hypertriglyceridemia." (PMID 33688365, 2021).
hypoxic-ischemic encephalopathy (1 paper, 2018). "In an in vitro study of hypoxic-ischemic encephalopathy (HIE), the cells suffering from hypoxia could have significantly increased levels of cleaved ATF6, which would promote apoptosis." (PMID 30283292, 2018).
infarction (1 paper, 2020). A localised pathological necrosis of tissue resulting from obstruction of the blood supply usually by a thrombus, an embolus, or vascular torsion. "ATF6 activation blunted infarction and preserved cardiac contractile function in an acute injury model being the first report demonstrating activated ATF6 could exert widespread protective effects in any tissue, in vivo." (PMID 32138230, 2020).
Legionella infection (1 paper, 2025). "Future studies focusing on the role of the ATF6, IRE1 and PERK axis of the UPR during Legionella infection, as well as their underlying mechanisms, will improve our understanding of how LegU1 modulates the UPR." (PMID 41162172, 2025).
lentivirus infection (1 paper, 2014). Virus diseases caused by the Lentivirus genus. "Then, we confirmed that the protein levels of ATF6α (p50) and phospho-eIF2αSer51, and the mRNA levels of CHOP and GRP78 in HeLa cells with stable SRECA2 knockdown were increased more significantly after exposure to SBF-1, compared with cells with stable NC lentivirus infection." (PMID 25522275, 2014).
leprosy (1 paper, 2018). Leprosy is a chronic infectious disease affecting primarily the skin and peripheral nervous system. "A statistically significant difference between the indeterminate, tuberculoid, and lepromatous clinical forms was detected, with high expression of GRP78/BiP, PERK, IRE1α, and ATF6 in tuberculoid forms (TT) when compared to lepromatous leprosy (LL) and indeterminate (I) leprosy." (PMID 30647798, 2018). "ATF6 was more expressed in TT (10.11 ± 2.38), followed by I (7.48 ± 1.77), and LL (6.93 ± 1.77) clinical forms, with statistical difference between TT and the other clinical presentations of leprosy." (PMID 30647798, 2018). "A total of 43 samples from leprosy patients were analyzed by immunohistochemistry with monoclonal antibodies against GRP78/BiP, PERK, IRE1α, and ATF6." (PMID 30647798, 2018).
lipodystrophy (1 paper, 2018). A congenital or acquired disorder characterized by abnormal loss or redistribution of the adipose tissue in the body. "We observed that the expression of ATF-4, ATF-6, PERK and C/EBP Homologous Protein (CHOP), were also increased in patients with lipodystrophy compared to control subjects." (PMID 29449893, 2018).
lung diseases (1 paper, 2018). "Little is known about role of ATF6 signaling in lung diseases." (PMID 30134920, 2018).
lung squamous cell carcinoma (1 paper, 2023). "Furthermore, a negative correlation between AGR2 and ATF6 was also reported in TCGA, lung squamous cell carcinoma (Spearman: − 0.104, p value: 0.02) and TCGA, pancreatic (Spearman: − 0.32, p value: 5.015e-3) cancer." (PMID 36899352, 2023).
memory impairment (1 paper, 2018). "Here we show that DREAM and transcriptionally active ATF6 are also reduced in the hippocampus and that chronic administration of repaglinide improves ATF6 processing and delays memory impairment in adult R6/1 mice." (PMID 29523177, 2018).
meningioma (1 paper, 2022). A generally slow growing tumor attached to the dura mater. "Moreover, our Ingenuity Pathway Analysis revealed that the transcription factors ATF3, ATF4, ATF6, and XBP1 were activated in meningioma cells exposed to DSF/Cu." (PMID 35453636, 2022).
mesothelioma (1 paper, 2017). A usually malignant and aggressive neoplasm of the mesothelium which is often associated with exposure to asbestos. "Tan I (5, 10, 20 and 40 μM) stimulated the expression of the ER stress markers such as IRE1and CHOP in the two mesothelioma cell lines, but not PERK, GRP78 and ATF6." (PMID 28212571, 2017).
metaphyseal chondrodysplasia type Schmid (1 paper, 2018). "Using knockdown in cell culture and gene ablation in mice we have directly compared the roles of ATF6α & β in responding to the increased ER stress induced by mutant forms of type X collagen that cause the ER stress-associated metaphyseal chondrodysplasia type Schmid (MCDS)." (PMID 29522813, 2018).
microcephaly (1 paper, 2025). A congenital or acquired developmental disorder in which the circumference of the head is smaller than normal for the person's age and sex. "Here, we report that deletion of activating transcription factor 6 (ATF6), consisting of ATF6α and ATF6β, in the developing brain caused microcephaly and neonatal death in mice." (PMID 40487428, 2025). "Here, we report that deletion of ATF6 in the developing brain causes microcephaly and neonatal death, the latter is associated with impaired milk suckling but not with impaired respiration." (PMID 40487428, 2025).
multiple epiphyseal dysplasia (1 paper, 2011). Multiple epiphyseal dysplasias (MED/EDMs) are characterized by epiphyseal anomalies causing joint pain early in life, recurrent osteochondritis and early arthrosis. "It remains unknown whether Xbp1 splicing, Atf6 proteolysis, or Eif2α phosphorylation occur in other mouse models of skeletal dysplasias characterized by ER stress, including the p.V194D Matn3 mutant model of multiple epiphyseal dysplasia, and an Aga2-mutant model of osteogenesis imperfecta." (PMID 21935428, 2011).
nutritional disease (1 paper, 2024). "The top-scoring network for the 9h-DEGs, also consisting of ATF3, ATF6, and DDIT3, was associated with cell-to-cell signaling and interaction, nutritional disease, and organismal injury and abnormalities (score = 41)." (PMID 39466820, 2024).
oral squamous cell carcinoma (1 paper, 2022). "The expression of certain ER stress markers such as PERK (PKR-like endoplasmic reticulum kinase), ATF6 (activating transcription factor 6), and GRP78 (glucose-regulated protein 78), was found to be upregulated in the oral squamous cell carcinoma (OSCC) tissues and related to poor overall survival." (PMID 35090495, 2022).
parasitic infection (1 paper, 2016). "These investigations would include determining the role of XBP-1 in resistance to oxidative stress due to Leishmania infection and examining other components of the ER stress signaling pathway, such as ATF6, in the context of parasitic infection." (PMID 27499755, 2016).
Peri-Implantitis (1 paper, 2024). An inflammatory process with loss of supporting bone in the tissues surrounding functioning DENTAL IMPLANTS. "PERK expression exceeded XBP1 significantly in FFF hyperplastic tissue, while expression levels of PERK, XBP1, and ATF6 were not significantly different in peri-implantitis and FBG tissues." (PMID 38730018, 2024).
periodontitis (1 paper, 2023). An acute or chronic inflammatory process that affects the tissues that surround and support the teeth. "To observe whether ERS occurs in visceral adipose tissue of rats with periodontitis, we detected the ERS-associated proteins GRP78, IRE1α, PERK and ATF6." (PMID 38129878, 2023). "qRT‒PCR analysis showed that the expression of GRP78, IRE1α and PERK in the periodontitis group was higher than that in the control group (P < 0.05), but ATF6 did not change." (PMID 38129878, 2023). "Compared with the control group, the periodontitis group exhibited higher expression of GRP78 and p-IRE1α/IRE1α (P < 0.05), but not p-PERK/PERK and ATF6." (PMID 38129878, 2023). "The results showed that the transcription and protein levels of GRP78 and IRE1α in the periodontitis group were significantly higher than those in the control group, and PERK and ATF6 were not changed." (PMID 38129878, 2023).
pheochromocytoma (1 paper, 2020). "RNA expression levels of RET gene with other pheochromocytoma-related genes and UPR markers, Bip/GRP78, CHOP, ATF4, and ATF6, in her pheochromocytoma relative to her normal adrenal gland were analyzed by real time PCR (RT-PCR)." (PMID 32571297, 2020). "Those of unfolded protein response markers, Bip/GRP78, CHOP, ATF4, and ATF6, were also increased in the pheochromocytoma." (PMID 32571297, 2020).
post-traumatic stress disorder (1 paper, 2025). An anxiety disorder precipitated by an experience of intense fear or horror while exposed to a traumatic (especially life-threatening) event. "The results of the conducted study provide significant evidence for the existence of associations between endoplasmic reticulum stress biomarkers (pPERK, IRE1α, ATF6) and the pro-inflammatory cytokine IL-18 with emotional regulation strategies in patients with post-traumatic stress disorder." (PMID 40806635, 2025).
preeclampsia (1 paper, 2017). Preeclampsia is a hypertensive disorder of pregnancy that is characterized by new-onset hypertension with proteinuria presenting after 20 weeks of gestation, and depending on mild or severe forms may initially present with severe headache, visual disturbances, and hyperreflexia. "Activation of placental UPR pathways including P-IRE1α, ATF6, XBP-1, GRP78 and GRP94 were all reported to be higher in early-onset (< 34 weeks) preeclampsia than in both late-onset preeclampsia and normotensive controls." (PMID 28397763, 2017). "Similarly, levels of ER stress markers such as PERK-induced p-eIF2α, ATF6 and XBP1u are increased in extravillous cytotrophoblasts, decidual cells and macrophages in decidual tissues derived from pregnancies complicated by FGR with or without preeclampsia." (PMID 28397763, 2017).
prostate tumor (1 paper, 2021). "Using different models of ER stress in various PCa cell lines and analyzing hundreds of prostate tumor samples, we discovered that Golgi proteases S1P and S2P can stay and function in the ER, thereby facilitating the cleavage of ATF6 and amplifying UPR." (PMID 34521429, 2021). "Depletion of ATF6 significantly blocks the growth of a prostate tumor, suggesting its potential implication in PCa therapy." (PMID 34521429, 2021). "Finally, depletion of ATF6 significantly retarded the growth of xenograft prostate tumors and blocks production of pro-metastatic metabolites." (PMID 34521429, 2021). "We found that advanced PCa cells utilize an alternative mechanism of ATF6-mediated UPR, thus simplifying stress response and promoting the maturation of proteins responsible for the growth of the prostate tumor, including those involved in AR signaling." (PMID 34521429, 2021). "Given that ATF6 signaling is the only Golgi-related response among the three UPR pathways, we hypothesized that advanced prostate tumor cells, which display a fragmented Golgi, may utilize a self-activating mechanism of sublethal ER stress." (PMID 34521429, 2021).
Pseudomonas infection (1 paper, 2016). Infections with bacteria of the genus pseudomonas. "In our study, early at 2 hrs after Pseudomonas infection, a lowering of ncRNAs preceded the up-regulation of the stress-activated transcription factors, ATF3 and ATF6, and the down-regulation of skin-enriched genes at 6 and 24 hrs." (PMID 27792773, 2016).